TGFA (transforming growth factor alpha)
Diseases named in the same sentence as TGFA in open-access papers (continued):
Sharing a sentence is not in itself a finding about the gene and the disease.
Obesity (14 papers, 2005 to 2025). Accumulation of substantial excess body fat. "For example, the Leprdb and Lepob-TGFα transgenic mouse model, used to investigate the effects of obesity on tumorigenesis, are leptin deficient or have a leptin receptor defect." (PMID 16168107, 2005). "For example, obesity due to increased inflammatory cytokine levels of transforming growth factor-alpha (TGF-α) and interleukin-6 (IL-6), in addition to stress due to the fight-and-flight response, leads to the activation of cortisol and catecholamines." (PMID 36648973, 2023). "Researchers have found that high‐fat diets and obesity may differentially modulate TGFA, potentially promoting tumor progression." (PMID 40119647, 2025).
osteosarcoma (14 papers, 2013 to 2024). A usually aggressive malignant bone-forming mesenchymal neoplasm, predominantly affecting adolescents and young adults. "MALAT1 can increase the expression of TGFA and promote the proliferation and metastasis of osteosarcoma by inhibiting mir376a." (PMID 35903358, 2022). "In this study, we investigated the mechanism underlying inhibitory effects of cisplatin on growth and proliferation of osteosarcoma cells, by analyzing the relationship between cisplatin, TGFA, and miR-376c." (PMID 32020849, 2021). "The relative expression of miR-376c in osteosarcoma tissue was significantly lower compared with normal skeletal muscle tissue (p < 0.001), and the expression of TGFA mRNA in osteosarcoma tissue was significantly higher compared with normal tissue (p < 0.001)." (PMID 32020849, 2021). "TGFA was silenced or overexpressed in Saos-2 osteosarcoma cells by transfection with TGFA-shRNA or TGFA ORF clone, respectively." (PMID 32020849, 2021). "In summary, cisplatin inhibited the proliferation of osteosarcoma cells Saos-2 by downregulating TGFA and upregulating miR-376c." (PMID 32020849, 2021). "Both in osteosarcoma tissues and Saos-2 cells, miR-376c expression was significantly decreased and TGFA mRNA expression was significantly increased compared with control." (PMID 32020849, 2021). "In osteosarcoma the PI3K / Akt / NF-kB pathway was activated after TGFα treatment, which promoted osteosarcoma metastasis." (PMID 26843615, 2016). "Ten years ago, from 600 cDNA microarray experiments of human osteosarcoma cell lines, five genes (Axl, TGFA, COLL7A1, WNT5A, and MKK6) have been identified and were associated with adherence, motility, and/or invasiveness of cancer cells." (PMID 24599309, 2014). "Previously, it has been found that TGFA has a critical role in the progression of osteosarcoma." (PMID 32020849, 2021). "Given that miR-376c exerted targeted inhibitory effects on TGFA expression, cisplatin may suppress the proliferation of osteosarcoma cells via the miR-376c/TGFA pathway." (PMID 32020849, 2021). "miR-376c can reduce the progression of osteosarcoma by targeting TGFA." (PMID 34322376, 2021). "MiR-376c and TGFA mRNA expression in osteosarcoma tissues showed a significant negative correlation (p < 0.001)." (PMID 32020849, 2021). "In our previous study, we determined that elevated ICAM-1 expression was promoted the metastasis of osteosarcoma: the expression level of ICAM-1 was elevated in two metastatic osteosarcoma cell lines and ICAM-1 siRNA reduced their tumor cell migration (transforming growth factor alpha)." (PMID 26503469, 2015).
psoriasis (13 papers, 2006 to 2025). An autoimmune condition characterized by red, well-delineated plaques with silvery scales that are usually on the extensor surfaces and scalp. "For example the production of transforming growth factor α (TGFα) by epidermal keratinocytes is greatly elevated in psoriasis." (PMID 23690852, 2013). "First, the two EGF-family ligands TGFα and HB-EGF, previously identified as a direct transcriptional target of PPARβ/δ, are highly upregulated in PPARβ/δ as well as in psoriasis, suggesting that EGF-receptor activation contributes to STAT3 phosphorylation." (PMID 20300524, 2010).
non-small cell lung carcinoma (12 papers, 1990 to 2024). A group of at least three distinct histological types of lung cancer, including non-small cell squamous cell carcinoma, adenocarcinoma, and large cell carcinoma. "Transforming growth factor-alpha (TGF-alpha)-mediated autocrine regulation in human non-small-cell lung cancer (NSCLC) cells NCI-H226 and its brain metastatic variant H226Br were compared." (PMID 8956792, 1996). "MiR-137 controls the occurrence and development of non-small cell lung cancer by regulating TGFA." (PMID 35903358, 2022). "The genes included the pathway non-small cell lung cancer were E2F2, E2F3, TGFA, PRKCG, CDK6, EGF, and CDK4, which were all expressed at significantly higher levels in LUSC tissues in comparison to that in the non-cancer group." (PMID 29394946, 2018).
endometrial cancer (11 papers, 2008 to 2024). Primary or metastatic malignant neoplasm involving the endometrium (mucous membrane that lines the endometrial cavity). "In conclusion, miR-490-3p has a tumor suppressor role in endometrial cancer and with c-Fos and TGFα as direct target gene." (PMID 26843615, 2016). "miR-505 suppressed tumorigenesis of endometrial cancer by targeting TGFA." (PMID 34322376, 2021). "After overexpressed of miR-490-3p in endometrial cancer cells the expression of TGFα was decreased, while EGFR and the downstream related genes including NF-kB, MMP-2, Cyclin D1, survivin were decreased in mRNA and protein level, while increased Bax expression." (PMID 26843615, 2016). "Above all, these results suggest that miR-490-3P may inhibit endometrial cancer tumorigenesis and progression through targeting TGFα." (PMID 26843615, 2016). "Besides, we found that miR-490-3P overexpression target TGFα in endometrial carcinoma." (PMID 26843615, 2016).
Ménétrier’s disease (10 papers, 2006 to 2025). "Overexpression of TGFA can cause a Ménétrier’s disease-like phenotype characterized by massive foveolar hyperplasia in mice." (PMID 41365858, 2025). "Our enrichment analysis showing downregulation of EGFR signaling during parietal cell differentiation in healthy gastric glands may explain the loss of parietal cell phenotypes in Ménétrier’s disease patients, where TGFα is overexpressed." (PMID 37386010, 2023). "Therefore, although high levels of TGFa can cause hypertrophic gastropathy, appropriate levels appear to maintain mucosal resistance to gastric injury." (PMID 16879752, 2006). "We previously established metallothionein (MT)-TGFA mice overexpressing TGFA and found that the mice can recapitulate the pathological features of Ménétrier’s disease." (PMID 41365858, 2025). "Ménétrier’s disease is a rare gastric lesion characterized by upregulation of TGFA/EGFR, giant rugal folds, and massive foveolar hyperplasia." (PMID 41365858, 2025). "Consistent with this, TGFα-overexpressing mice recapitulated the characteristics of Ménétrier’s disease, such as substantial pit cell hyperplasia and a marked reduction of parietal cells and chief cells." (PMID 37386010, 2023). "Taken together, Rab25 loss can promote pit cell commitment by enhancing TGFA secretion in gastric epithelial cells, and excessive TGFA secretion due to loss of Rab25 can cause EGFR activation and lead to a stomach phenotype resembling human Ménétrier’s disease." (PMID 41365858, 2025). "Overexpression of TGFA causes an alteration of gastric lineage cell commitment towards pit cells, and aberrant TGFA/EGFR signaling is also associated with the development of a rare hypertrophic disorder, Ménétrier’s disease, characterized by massive foveolar hyperplasia." (PMID 41365858, 2025). "Upregulated expressions of transforming growth factor alpha (TGF-α) and epidermal growth factor receptor (EGFR) in the gastric mucosa of individuals diagnosed with Ménétrier’s disease have been demonstrated." (PMID 31123980, 2019). "Also, EW disrupts TGFα- EGFR pathway by increasing signaling, which in transgenic animals and Mènètrier’s disease reduces ZC and PC number, respectively." (PMID 31892140, 2019). "A decade ago, one of the authors, H. Takagi, generated TGFα-expressing TG mouse lines under the control of the metallothionein gene promoter, and one of these lines (MT100) exhibited hypertrophic gastropathy resembling Menetrier's disease, as similarly shown by other investigators." (PMID 16879752, 2006).
liver cancer (9 papers, 2004 to 2024). An epithelial or non-epithelial malignant neoplasm that arises from the liver. "We also employed mice that carried a liver cancer driver transgene, TGFα, and used bi-transgenic mice encoding both TGFα/TrsptG37 transgenes." (PMID 23460847, 2013). "Transforming growth factor α (TGFα) is one of the cytokines, causally involved in the pathogenesis of liver cancer." (PMID 15534611, 2004). "Earlier studies involving selenium and tumor formation examined the role of dietary selenium on liver cancer in TGFα/c-Myc mice, wherein hepatocarcinogenesis was suppressed by both selenium deficiency and high levels of selenium." (PMID 23460847, 2013). "These latter bi-transgenic mice developed tumors within 6 months and c-Myc, which is also known to be a liver cancer driver, along with TGFα, shortened the time of tumor development considerably compared to TGFα alone." (PMID 23460847, 2013). "Considering the upregulation of TGFα in human malignancies, including liver cancer, hope focuses on the possible therapeutic benefit of blocking TGFα-evoked signal transduction on the cell surface, for example, by blockade of the receptor or of ligand–receptor interactions." (PMID 15534611, 2004). "A diet lacking selenium also reduced tumor incidence in TGFα/c-Myc transgenic mice; these mice have disrupted redox homeostasis and develop liver cancer by 6 months of age." (PMID 39064692, 2024).
oral cancer (9 papers, 1994 to 2022). "Increased transcription of TGFA, encoding for the cognate ligand TGFα, has also been reported in vitro in oral cancers." (PMID 35163485, 2022). "The blocking effect of MK2206, a pAkt inhibitor, suggested that TGFα-stimulated oral cancer cell migration might be Akt signalling pathway-dependent." (PMID 35681586, 2022). "Research provided evidence that mRNA and protein levels of TGFα and EGFR increased in oral cancer patients in comparison to disease-free controls and poor prognosis might be related to this elevation level of TGFα and EGFR." (PMID 35681586, 2022). "mRNA levels of TGFα and EGFR also increased in the normal mucosa of oral cancer patients, suggesting that TGFα/EGFR gene transcription is an early event of carcinogenesis or could be a foundation to a tumour." (PMID 35681586, 2022). "Moreover, four genes (SERPINB2, GFOD1, TGFA, MXD1) were downregulated in these samples suggesting an inhibitory role in oral cancer cell invasion and metastasis." (PMID 34116687, 2021). "TGFα and EGFR also been reported to play important role in the proliferation of oral cancer cells but not in the proliferation of normal epithelium." (PMID 35681586, 2022).
osteoarthritis (9 papers, 2009 to 2024). A noninflammatory degenerative joint disease occurring chiefly in older persons, characterized by degeneration of the articular cartilage, hypertrophy of bone at the margins and changes in the synovial membrane. "FEPIXNEBART, a drug that targets TGFA, is administered for the management of osteoarthritis, low back pain, and neuropathic pain, among other conditions." (PMID 39722126, 2024). "For seven genes (ALDH1A2, CHMP1A, CRADD, FAM53A, LTBP1, RPP25, and TGFA), we found evidence that GWAS signals for osteoarthritis colocalize with mQTLs in these genes and are additionally associated with gene expression levels in the same tissue." (PMID 35679866, 2022). "Several of these SNVs, rs3771501 (TGFA), rs3993110 (TEAD1/DKK3), rs72979233 (CHRDL2), and rs7967762 (PFKM/WNT10B), are associated with multiple osteoarthritis joint sites." (PMID 34450027, 2021). "We found such an eQTL effect below nominal significance levels for five genes in low-grade osteoarthritis cartilage (ALDH1A2, CHMP1A, FAM53A, RPP25, and TGFA), two genes in high-grade osteoarthritis cartilage (FAM53A and LTBP1), and one gene in synovium (CRADD)." (PMID 35679866, 2022). "Transforming growth factor alpha (TGFα) is a growth factor involved in osteoarthritis (OA)." (PMID 27457421, 2016). "TGFα and HB-EGF were found to be elevated in degenerated osteoarthritis cartilage." (PMID 38004424, 2023). "However, EGFR activation by intra-articular administration of TGFα, rather than EGFR inhibition, was reported to attenuate osteoarthritis pain." (PMID 38004424, 2023).
renal cell carcinoma (9 papers, 1998 to 2022). "Interestingly, TGFA expression has recently been linked to therapeutic responses in renal cell carcinoma." (PMID 34399807, 2021). "This study unveils a distinctive feature in renal cell carcinomas, which is the presence of membrane-anchored TGFα." (PMID 34399807, 2021). "Epidermal growth factor receptor (EGFR) and tumour growth factor alpha (TGFα) are frequently overexpressed in renal cell carcinoma (RCC) yet responses to single-agent EGFR inhibitors are uncommon." (PMID 15956968, 2005). "Therefore, it is also possible that USF2 also participates in the HIF2α-dependent expression of PHD3, OCT-4, NDRG1, TGFA, GLUT1, CCND1 and SLC7A5 in renal cell carcinoma." (PMID 33321829, 2020).
Stroke (9 papers, 2014 to 2025). Sudden impairment of blood flow to a part of the brain due to occlusion or rupture of an artery to the brain. "Consistent with previous studies employing TGFα as a therapeutic approach in stroke mouse models, our study suggests a therapeutic potential of TGFα to mitigate CNS inflammation worthy of further studies." (PMID 40537468, 2025). "Specifically, there are reports that TGFA contributes to enhancing the repair mechanism after nervous system post-stroke and post-traumatic injury." (PMID 36012250, 2022). "In models of middle cerebral artery occlusion in mice and rats, TGFA treatment significantly reduced infarct size, suggesting that TGFA can induce angiogenesis, neurogenesis, and neuroprotection after stroke." (PMID 30670929, 2018). "It is hypothesized that TGFA could improve or the state of neurodegenerative disorders, such as Parkinson’s disease, as well as post-traumatic and stroke brain injury, and even reverse some of their characteristic features." (PMID 33946816, 2021).
bladder cancer (8 papers, 1996 to 2024). "It has been reported that circTAF4B promotes TGFA expression by sponging miR‐1298‐5p, thereby promoting proliferation and epithelial–mesenchymal transition in bladder cancer cells." (PMID 39513664, 2024). "Preclinical studies demonstrated that TGFα-immunotoxins are highly cytotoxic to bladder cancer cells and patient bladder cancer explants, despite the lack of EGFR amplification in these cells." (PMID 27153091, 2016). "Bladder cancers rely upon TGFα as the primary EGFR ligand, suggesting that therapeutics utilizing TGFα as a targeting agent would be beneficial for treatment of these malignancies." (PMID 27153091, 2016).
diabetes (8 papers, 2013 to 2025). "In this study, we have identified a group of APMB-specific analytes (IL-10, CXCL1, IL-12p40, IL-13, CCL22, CCL4, IL-17A, and TGFα) that correlates with several clinical phenotypes associated with more severe SAB (diabetes, dialysis dependence, metastatic infection, and cardiac vegetation)." (PMID 39966757, 2025). "In our previous investigation, we found that AhR regulated the energy balance, insulin sensitivity, and glucose metabolism in the diabetes condition involved in the regulation of the VEGFβ- and TGFα pathway." (PMID 36232555, 2022). "Suppressing NO synthesis could aggravate diabetes and complications by stimulating TGFα." (PMID 35955706, 2022).
breast tumor (7 papers, 1989 to 2026). "The overall survival and breast tumor-specific survival rates were both higher in the FGFR4-deficient TGFα transgenic mice than the FGFR4-WT TGFα transgenic mice." (PMID 24279986, 2013). "TGFα, whose overexpression drives the breast tumors in the mouse model studied here, is closely related to EGF and an activating ligand for the proto-oncogene Her2, also called Neu or ErbB-2, a member of the EGFR family." (PMID 24279986, 2013). "However, upon MMTV-promoter-driven TGFα overexpression, both KO-Tg and Tg female mice started to develop palpable breast tumors that disrupted the normal breast tissue structure 4 to 6 months after birth." (PMID 24279986, 2013). "Breast tumors were induced in the bigenic mice with ablation of FGFR4 and overexpression of TGFα that activates Her2 in the ductal and lobular epithelium surrounded by adipocytes." (PMID 24279986, 2013). "However, the absence of FGFR4 reduced TGFα–driven breast tumor incidence and progression and improved host survival." (PMID 24279986, 2013). "Phospho-tyrosine (active) kinase antibody array analyses on breast and breast tumor tissues revealed that the activities of both EGFR (Her1) and Her2 were enhanced about 7.5-fold in the TGFα transgenic mice relative to the non-transgenic controls." (PMID 24279986, 2013).
cleft palate (7 papers, 2012 to 2024). Cleft palate is a fissure type embryopathy that affects the soft and hard palate to varying degrees. "The methods are applied to analyze cleft palate data of the TGFA gene of an Irish study to show the association found previously." (PMID 24007308, 2013). "In summary, the association between TGFA gene and cleft palate is only confirmed by 3 out of 5 proposed models." (PMID 24007308, 2013). "The reported association between the TGFA gene and cleft palate is confirmed by the proposed Dom, Add, and Mult models." (PMID 24007308, 2013). "In humans, the cleft palate has been associated with polymorphism in TGFA gene, encoding for TGF-α, thus linking this condition to the EGF pathway." (PMID 34955078, 2022). "The methods are applied to test for association between transforming growth factor alpha (TGFA) gene and cleft palate in an Irish study." (PMID 24007308, 2013). "The methods are applied to test for association between the transforming growth factor alpha (TGFA) gene and cleft palate in the Irish study." (PMID 24007308, 2013).
fibrosis (7 papers, 2005 to 2025). the formation of excess fibrous connective tissue in an organ or tissue in a reparative or reactive process. "This pattern of pleural and peribronchial fibrosis has previously been reported in mice with pulmonary overexpression of TGFα." (PMID 41150169, 2025). "Of interest, we found that TGFα and TGFβ immunoreactivity was significantly high in mice that develop foci of subpleural fibrosis after cigarette-smoke or BLM treatment when a positive reaction for mouse NE on the alveolar septa was found." (PMID 16045796, 2005). "We used a transgenic mouse model of chronic lung disease induced by the overexpression of transforming growth factor-alpha (TGF-α), established by the presence of pleural and peribronchial fibrosis and impaired lung mechanics determined by the forced oscillation technique and plethysmography." (PMID 28473708, 2017).
head and neck cancer (7 papers, 2007 to 2023). A primary or metastatic malignant neoplasm affecting the head and neck. "The cellular components synthesise growth factors such as EGF, TGFα and β, VEGF, and NGF, which have been shown to initiate paracrine signalling in head and neck cancer cells by binding to cell surface receptors." (PMID 35681586, 2022).